SERPINB5 (serpin family B member 5)
Description:
Tumor suppressor. It blocks the growth, invasion, and metastatic properties of mammary tumors. As it does not undergo the S (stressed) to R (relaxed) conformational transition characteristic of active serpins, it exhibits no serine protease inhibitory activity.
Synonyms: PI5; maspin
Tractability: Small molecule: it has a high-quality binding pocket. Antibody: UniProt places it where antibodies can reach, with medium confidence; its Gene Ontology location is reachable by antibodies, with medium confidence. PROTAC: ubiquitination databases record sites on it.
Gene: Protein-coding gene on chromosome 18 (63,476,945 to 63,505,085, forward strand). Ensembl gene ENSG00000206075.
Subcellular location: Secreted, extracellular space
Subcellular location (Human Protein Atlas): Vesicles
Gene Ontology:
Molecular function: protein binding; serine-type endopeptidase inhibitor activity
Cellular component: cytoplasm; apical part of cell; cell surface; cornified envelope; extracellular region
Genetic constraint (gnomAD): Loss-of-function variants: 24 observed, 29.53 expected, observed/expected ratio (o/e) 0.81, 90% interval 0.59 to 1.14. The upper end of that interval is the gene's LOEUF score, 1.14, which puts it in group 5 of 6, group 1 being the genes least tolerant of losing a copy. Missense variants: 359 observed, 405.23 expected, observed/expected ratio (o/e) 0.89, 90% interval 0.81 to 0.97. Synonymous variants: 147 observed, 151.55 expected, observed/expected ratio (o/e) 0.97, 90% interval 0.85 to 1.11.
Homologues: Orthologues: chimpanzee SERPINB5 (99% identical), macaque SERPINB5 (99% identical), pig SERPINB5 (93% identical), dog SERPINB5 (93% identical), rabbit SERPINB5 (93% identical), guinea pig Serpinb5 (91% identical), mouse Serpinb5 (89% identical), rat Serpinb5 (89% identical), tropical clawed frog serpinb5 (54% identical). Paralogues in human: SERPINB1 (39% identical), SERPINB10 (38% identical), SERPINB8 (37% identical), SERPINB6 (37% identical), SERPINB3 (35% identical), SERPINB9 (35% identical), SERPINB4 (35% identical), SERPINB2 (34% identical), SERPINB11 (34% identical), SERPINB13 (34% identical), SERPINB12 (32% identical), SERPINB7 (32% identical), and 24 more.
Diseases named in the same sentence as SERPINB5 in open-access papers:
SERPINB5 is named in the same sentence as 68 diseases in open-access papers, as found by Europe PMC text mining. Sharing a sentence is not in itself a finding about the gene and the disease. The quoted sentences say what the papers report.
breast cancer (31 papers, 2010 to 2025). A primary or metastatic malignant neoplasm involving the breast. "Serpin B5, which is a 42 kDa serine proteaseinhibitor encoded by gene SERPINB5 located at band 18q21.33, is proposed asa tumor suppressor and found to be downregulated in breast cancer." (PMID 33884102, 2021). "We also found protective associations between higher GReX of AURKA (20q13.2), PIK3CA (3q26.32), and SERPINB5 (18q21.33) and lower risk of breast cancer mortality." (PMID 32079541, 2020). "SERPINB5 promotes apoptotic events of invasive prostate and breast carcinoma cells and down-regulation of its expression causes pancreatic, colorectal, and ovarian adenocarcinomas." (PMID 25020046, 2014). "The tumor tumor-suppressive role of SERPINB5 in breast cancer is also supported by experimental evidence." (PMID 38166892, 2024). "SERPINB5 (serine protease inhibitor b5), initially identified in breast cancer, serves as a tumor suppressor by suppressing metastasis and angiogenesis, as well as promoting cell adhesion and apoptosis." (PMID 38426148, 2024). "SerpinB5 has been reported to inhibit cell motility, invasion, and metastasis in breast cancer cell models." (PMID 36159573, 2022). "We next examined the SERPINB5 gene, which encodes the tumor suppressor maspin and is methylated and transcriptionally silenced in human MDA-MB-231 breast cancer cells." (PMID 34588447, 2021). "Serpin family B member 5 (SERPINB5), also known as MASPIN, was first reported to function as a tumor repressor gene in breast cancer." (PMID 32005234, 2020). "Some of the enriched epithelial genes or cytokine genes have been reported to get involved in cancer development and progression, for example, SERPINB5 in breast cancer, CCL3L1 in glioblastoma, CXC group in lung cancer, MMP28 in gastric cancer and so on." (PMID 32309224, 2020). "FOXO1 is known to be regulated by miR-27a, miR-96, and miR-182 in breast cancer cells, SERPINB5 is regulated by miR-21, and STARD10 is regulated by miR-661." (PMID 28793339, 2017). "SERPINB5, also known as the mammary tumor suppressor Maspin, was also identified as a likely MAGI3 interactor." (PMID 27205883, 2016). "SERPINB5 is downregulated in breast cancer, and has the ability to modify the motility of breast cancer cells in vitro by inhibiting Rac1/Cdc42 activity." (PMID 27418879, 2016). "Mammary Serine Protease Inhibitor (Maspin, SERPINB5) was identified in normal mammary epithelia and invasive mammary cancer cells." (PMID 26263377, 2015). "SERPINB5, also known as maspin (mammary serine protease inhibitor) is a class II tumor suppressor gene identified in patients with breast cancer." (PMID 25020046, 2014). "mir21, as a master regulator of the metastatic processes was found to stimulate cell invasion by targeting tumor suppressors TPM1, PDCD4 and SERPINB5 in breast cancer or colon cancer." (PMID 24069219, 2013). "Maspin is a member of the serpin family of protease inhibitors (SERPINB5) and has been described as an epithelial marker and a type II tumor suppressor gene based upon its ability to inhibit invasion and motility of mammary tumors." (PMID 21559267, 2011). "SERPINB5 is regarded as a metastasis suppressor gene in breast cancer, but has also been proposed as a detector of circulating breast cancer cells." (PMID 20939879, 2010). "SERPINB5, also called MASPIN, was first identified as a tumor suppressor in breast cancer models." (PMID 41037786, 2025). "SERPINB5 has been indicated to inhibit tumor progression, DSC3 downregulation has been linked with several cancer types and GABRP over-expression has been linked with poor prognosis, metastatic cancer, basal-like breast cancer." (PMID 39580456, 2024). "Moreover, 318 over-represented proteins were common in the three carcinoma cell lines, including SERPINB5 among the most abundant proteins, which is expressed in highly aggressive human basal-like breast cancers." (PMID 39462388, 2024).
breast cancer (continued). "However, immunohistochemistry staining in a subsequent study revealed higher SERPINB5 expression levels in patients with breast cancer who had worse prognosis, complicating matters." (PMID 32005234, 2020). "However, a simple SerpinB5 cDNA transfection in TM40D mammary tumor cells resulted in SerpinB5 in the cytoplasm only, suggesting that SerpinB5 requires an active mechanism to translocate to the nucleus." (PMID 27447178, 2016). "SERPINB5 (9.8-fold) is strongly associated to breast cancer metastasis and negative prognostic in pancreatic cancer." (PMID 22905093, 2012). "Therefore, upregulated SerpinB5 and downregulated Amtn may be involved in suppressing mammary cancer development and lymph node metastasis in SB2−/−;PyMT mice." (PMID 35768767, 2022). "This conditional analysis suggests that the GReX of AURKA, CAPN13, and SERPINB5 may be associated with breast cancer-specific survival independent of the GWAS-identified variant." (PMID 32079541, 2020). "In addition, SERPINB5 can potently inhibit the development of brain metastasis of breast cancer." (PMID 27418879, 2016). "When we applied heteroDE to breast cancer samples, we identified 7 cfRNA biomarkers (SCGB2A2, CASP14, FABP7, CRABP2, VGLL1, SERPINB5, TFF1), 3 of which (FABP7, SCGB2A2, CASP14) overlap with previously identified DCB genes." (PMID 33883548, 2021). "Less is known about the involvement of SERPINB5 and CAPN13 in breast cancer survival, though they have been identified in studies into breast cancer progression." (PMID 32079541, 2020). "We found that hsa-miR-21 and has-miR-96 forms the interaction model mostly with oncogenes, but hsa-miR-10b forms three interaction models with tumor suppressors, FOXO1, SERPINB5, and STARD10, to have statistical dependency on breast cancer." (PMID 28793339, 2017). "LAMA3 is not a known tumor suppressor but SERPINB5, also known as maspin, has well-established tumor suppressor activity in breast cancer." (PMID 34680217, 2021). "FOXO1, SERPINB5, and STARD10 are putative breast cancer suppressor." (PMID 28793339, 2017).
gastric cancer (14 papers, 2010 to 2025). A primary or metastatic malignant neoplasm involving the stomach. "SERPINB5 has been implicated in an oncogenic role in gastric cancer." (PMID 38612418, 2024). "According to bioinformatics databases, SERPINB5 mRNA expression was higher in gastric cancer than normal tissues (p < 0.05), and negatively correlated with depth of invasion, TNM staging and dedifferentiation of gastric cancer (p < 0.05)." (PMID 29029529, 2017). "Among the down-regulated genes, the expression level of SERPINB5 is negatively associated with the depth of invasion, metastasis, and TNM stage in gastric cancer." (PMID 22078224, 2011). "In gastric cancer (GC), SERPINB5 upregulates ITGB1 and promotes epithelial mesenchymal transition (EMT), while MFAP2 also upregulates ITGB1." (PMID 38279122, 2024). "Maspin (SERPINB5) overexpression correlates with increased metastasis and poor outcome in PDAC and gastric cancer." (PMID 26993610, 2016). "In TCGA data, SERPINB5 expression was higher in gastric cancers with than without Barret’s esophagus (p < 0.05)." (PMID 29029529, 2017). "However, there is no more in-depth study on SerpinB5 promoting the occurrence and development of gastric cancer." (PMID 37006240, 2023).
pancreatic cancer (14 papers, 2010 to 2025). "SERPINB5 has been related to good prognosis in lung, prostate, head and neck, and skin cancer, whereas in pancreatic cancer, it is associated with a poor prognosis." (PMID 28687755, 2017). "SERPINB5 has been previously associated with pancreatic cancer." (PMID 32024004, 2020). "Thepredicted survival probability is much higher for pancreatic cancer patients with low mRNAexpression of FN1 or SERPINB5." (PMID 33884102, 2021). "Interestingly, most of the relationships between drug resistance and the expression levels of the up-UDEGs ANLN, GPRC5A and SERPINB5 were positive, indicating that these three genes are closely related to the resistance mechanisms of pancreatic cancer." (PMID 40362181, 2025). "Indeed, in clinical samples, the presence of unmethylated SERPINB5 has demonstrated its potential as a specific biomarker for pancreatic tumors, enabling the differentiation of pancreatic ductal adenocarcinoma (PDAC) from pancreatitis." (PMID 37798621, 2023). "Several reports have shown that the over-expression of SERPINB5 (serine protease inhibitor B5) can promote PDAC metastasis, and the marked up-regulation of SLC6A14 (solute carrier, family 6, member 14) in pancreatic cancer leads to worse survival." (PMID 40362181, 2025). "We analyzed mRNA expression levels of MYEOV, GPRC5A, KRAS, EGFR, SERPINB5, EIF4G2, and PDCD4 in pancreatic cancer tissues and normal tissues adjacent to pancreatic cancer from three pancreatic cancer patients." (PMID 36358856, 2022). "We also validated the role of ceRNA network genes such as GPRC5A, SERPINB5, KRAS, EGFR, EIF4G2, and PDCD4 in pancreatic cancer." (PMID 36358856, 2022). "It was found that MYEOV, GPRC5A, SERPINB5, KRAS, EGFR, and EIF4G2 were all significantly elevated in pancreatic cancer tissues, and the expression trends of GPRC5A, SERPINB5, KRAS, EGFR, and EIF4G2 in different stages were nearly identical." (PMID 36358856, 2022). "Among the five top DEGs, overexpression of SERPINB5, HOXA10 and KRT16 at the mRNA level has previously been reported in pancreatic cancer." (PMID 28418924, 2017). "It was noted that MYEOV could serve as a ceRNA by producing molecular sponging effects on hsa-miR-103a-3p and hsa-miR-107, thus affecting the role of GPRC5A, SERPINB5, EGFR, KRAS, EIF4G2, and PDCD4 on pancreatic cancer progression." (PMID 36358856, 2022). "To investigate whether MYEOV acts as ceRNA to exert certain regulatory effects on genes such as GPRC5A, SERPINB5, KRAS, EGFR, EIF4G2, and PDCD4, we analyzed the differential expression of these genes in pancreatic cancer and normal pancreatic tissues by the GEPIA database." (PMID 36358856, 2022). "Thus, an assay determining SERPINB5 promoter methylation, or rather lack of methylation, may be considered as a marker for pancreatic cancer." (PMID 20939879, 2010).
lung cancer (12 papers, 2012 to 2025). A malignant neoplasm involving the lung. "Compared with normal lung tissue cells, the SERPINB5 gene is specifically expressed at high levels in lung cancer cells and can be used as a diagnostic marker of lung cancer." (PMID 35846148, 2022). "Overexpression of SERPINB5 has been associated with cancer progression and a poor prognosis in lung cancer." (PMID 22768131, 2012). "Lung cancer patients with a high SERPINB5 expression had a poorer overall survival time than those with a low SERPINB5 expression." (PMID 37692503, 2024). "SERPINB5 has been identified as a hub gene in lung cancer patients." (PMID 37692503, 2024). "Although the role of this molecule is largely unknown, SERPINB5 seems to act as a tumor suppressor through the inhibition of cancer cell migration, invasion capability, and angiogenesis, suggesting a compensatory mechanism in CS and COPD patients in the relationship between COPD and lung cancer." (PMID 40243422, 2025).
prostate carcinoma (10 papers, 2009 to 2025). A carcinoma that arises from epithelial cells of the prostate gland. "SERPINB5 is less well known; its transcript was decreased in PCa samples in this study, which would fit with its role in tumour inhibition, with loss or decreased expression of SERPINB5 being reported in prostate cancer cells." (PMID 35454901, 2022). "Serpinb5, referred to as Maspin (mammary serine protease inhibitor), was identified as a serine protease inhibitor and recognized as a tumor suppressor, and its loss has been observed in breast and prostate cancers, making it a promising diagnostic marker for monitoring tumor progression." (PMID 38539447, 2024). "Of note, SERPINB5 (maspin) found to be significantly downregulated in cases 8, 11 and 12 versus case 5, is a candidate tumor suppressor in prostate cancer." (PMID 24416450, 2014). "SERPINB5 (serpin peptidase inhibitor, clade B (ovalbumin), member 5) is implicated as a tumor suppressor which is absent in breast and prostate cancer and has also a possible causal role in metastasis." (PMID 25857299, 2015). "The data of the TCGA database demonstrated that those PCa patients who showed low SERPINB5 and high BIRC5 transcript expression were characterized by a reduced disease-free survival rate, thereby highlighting the clinical relevance of the activation of the NFκB pathway in human prostate cancer." (PMID 32640711, 2020). "It will be attractive to verify if carcinogenesis of prostate cancer cells were due to such coordinated epigenetic switches of these SERPINB genes, since some of them are known tumor suppressor genes, such as SERPINB2 and SERPINB5, and can contribute to decreased tumor growth and metastasis." (PMID 19262738, 2009).
colorectal cancer (7 papers, 2016 to 2022). A primary or metastatic malignant neoplasm that affects the colon or rectum. "In colorectal cancer, SERPINB5 overexpression is associated with poor overall survival and progression-free survival." (PMID 35800432, 2022). "A decreased expression of the tumor suppressor, SerpinB5, was only observed in resistant colorectal cancer variants." (PMID 31344863, 2019). "But SERPINB5 is regarded as a metastasis suppressor in breast and colorectal cancer." (PMID 26993610, 2016). "In addition, SERPINB5 was demonstrated to be a biomarker for colorectal cancer that interacts with carcinoembryonic antigen (CEA), which has been already approved as a clinical marker, and was shown to increase tumor cell invasion and angiogenesis in human mammary epithelial cells." (PMID 32503295, 2020). "A report hypothesized that SERPINB5 (also known as maspin) might play a role in dysregulating the intestinal microbiota and inducing idiopathic inflammatory bowel disease (IBD)-related colorectal carcinoma." (PMID 36699448, 2022).
pancreatic ductal adenocarcinoma (6 papers, 2010 to 2025). An infiltrating adenocarcinoma that arises from the epithelial cells of the pancreas. "However, SERPINB5 disregulation occurs early during multi-step progression models of ductal pancreatic adenocarcinomas, and its overexpression associated to dismal prognosis, as we found in LUAD." (PMID 30473748, 2018). "SERPINB5 over-expression has been shown to promote metastasis in pancreatic ductal adenocarcinoma, and knockdown of SERPINB5 reduced the primary tumor weight and significantly decreased the amount of metastasis." (PMID 40362181, 2025). "illustrated that upregulated SERPINB5 expression was correlated with increased metastasis resulted from SERPINB5 methylation in pancreatic ductal adenocarcinoma." (PMID 35800432, 2022). "In pancreatic ductal adenocarcinoma (PDAC), SERPINB5 appears to function as an oncogene, and unmethylated SERPINB5 has been identified as a specific marker for PDAC in clinical samples, suggesting its potential utility for liquid biopsies." (PMID 38612418, 2024).
lung adenocarcinoma (5 papers, 2022 to 2024). A carcinoma that arises from the lung and is characterized by the presence of malignant glandular epithelial cells. "BTG2 and SerpinB5 were studied as a gene pair in our article to investigate their prognostic value in lung adenocarcinoma." (PMID 37006240, 2023). "Survival analysis shows that COL5A2 and SERPINB5 are significant for identifying lung adenocarcinoma and are considered biomarkers of lung adenocarcinoma." (PMID 35846148, 2022).
cervical carcinoma (4 papers, 2017 to 2026). A carcinoma arising from either the exocervical squamous epithelium or the endocervical glandular epithelium. "Loss-of-function experiments demonstrate that SERPINB5 depletion sensitizes cervical cancer cells to paclitaxel and vincristine, while its reintroduction restores chemoresistance even in m5C-deficient cells." (PMID 41673397, 2026). "Our study uncovers a previously unrecognized m5C-SERPINB5 axis as a central driver of cervical cancer malignancy and chemoresistance, highlighting SERPINB5 as a clinically actionable target to improve outcomes for patients receiving microtubule-targeting chemotherapy." (PMID 41673397, 2026).
preeclampsia (4 papers, 2013 to 2020). Preeclampsia is a hypertensive disorder of pregnancy that is characterized by new-onset hypertension with proteinuria presenting after 20 weeks of gestation, and depending on mild or severe forms may initially present with severe headache, visual disturbances, and hyperreflexia. "The development of preeclampsia is also depicted by the increased level of unmethylated fetal SERPINB5 in maternal blood." (PMID 32849827, 2020). "In addition, the expression of maspin (SERPINB5), a serine protease inhibitor and an inhibitor of cell migration, which may modify trophoblast cell invasion in the first trimester, could also be modified in preeclampsia." (PMID 26300992, 2015).
breast tumor (3 papers, 2016 to 2024). "Among others, SERPINB5, DSC3, and GABRP have also been linked with malignant neoplasms of the breast." (PMID 39580456, 2024). "Other up-regulated proteins of interest with possible roles in regulating breast tumor cell progression included DPYSL2, FAM129B, IL18, NDRG1, NME1, and SERPINB5." (PMID 28174229, 2017).